HLA-C (major histocompatibility complex, class I, C)
Diseases named in the same sentence as HLA-C in open-access papers (continued):
Sharing a sentence is not in itself a finding about the gene and the disease.
psoriasis (continued). "A meta-analysis of eight studies including 1048 psoriasis patients showed that HLA-C*06:02 positive patients had a median PASI75 response rate of 92% after 6 months of ustekinumab therapy compared to a median PASI75 response rate of 67% in the HLA-C*06:02 negative patients." (PMID 35154085, 2021). "The most important genetic marker for psoriasis is HLA-C*06, also known as PSOR1." (PMID 34127053, 2021). "HLA-C*06:02 is located at the PSORS1 locus and the role of HLA-C*06:02 in psoriasis is well known." (PMID 31902555, 2020). "Another hypothesis postulates that this psoriasis subtype may be triggered by autoantigens presented in the context of HLA-C*06:02 to CD8+ T-cells, which are abundant in psoriasis epidermis and are highly dependent on IL23." (PMID 33419370, 2020). "When we conditioned on HLA-C and NOTCH4, we observed an independent association at HLA-B amino acid position 67 (B-Y67C, OR = 1.80, P = 5.45 × 10−11), which was previously reported to be associated with psoriasis in both European and Han Chinese populations." (PMID 33134369, 2020). "However, due to the lack of antigen‐specific CD8+ T‐cell responses in HS patients, the link between the presence of SNPs in the HLA‐C region/ERAP1 gene and susceptibility to paradoxical psoriasis is apparently missing." (PMID 31577850, 2020). "While Hashimoto’s thyroiditis is associated with HLA class II alleles, class I HLA, specifically HLA-C allele, which is strongly associated with early-onset psoriasis, is not implicated in Hashimoto’s susceptibility." (PMID 31157131, 2019). "Psoriasis and PsA are associated with class I MHC alleles, mainly HLA-C*06, which is a major risk factor for psoriasis but not for PsA43." (PMID 31583079, 2019). "HLA-C⁎06 and HLA-C⁎12 were significantly more frequent in the psoriasis group." (PMID 31341424, 2019). "In psoriasis, HLA-C*06:02 facilitates a T-cell mediated skin-specific autoimmune response." (PMID 29760713, 2018). "Similarly to AS and BD, further investigation revealed significant evidence for the interaction between ERAP1 and HLA-C loci in psoriasis, with a combined significance of P = 6.95 × 10−6." (PMID 30054427, 2018). "Using a paradigmatic Vα3S1/Vβ13S1-TCR from an epidermal CD8+ T-cell clone of an HLA-C*06:02-positive psoriasis patient, we could identify melanocytes as HLA-C*06:02-restricted target cells of the psoriatic immune response." (PMID 29760713, 2018). "Interestingly, a recent study has revealed a new pathway for the pathogenesis of psoriasis i.e., a melanocyte-specific response pathway where HLA-C*06:02 produces an autoimmune response against melanocytes by antigen presentation." (PMID 29292715, 2017). "Given the role of HLA-C in antigen presentation, it has been hypothesized that HLA-Cw6 may have a high binding affinity for one or more psoriasis autoantigens." (PMID 29186830, 2017). "We noticed that almost all MethQTL SNPs were located around HLA-C gene, suggesting that they may have important role similar to HLA-C in the etiology of psoriasis." (PMID 27980695, 2016). "SNPs in the TNFAIP3 gene, but also in other immune-regulatory genes including HLA-C, TNIP1/ABIN-1 and IL-23A have been associated to psoriasis and polymorphisms in the TNFAIP3 gene correlate to responsiveness to TNFα blockers in psoriasis patients." (PMID 26124703, 2015). "However, among the individuals with late psoriasis (over 40 years of age) and HLA-C*06 positivity, the age at onset of psoriasis was significantly younger in men (44.3 ± 3.2 years) than in women (57 ± 4.2 years), P < 0.01." (PMID 23690822, 2013). "Our findings confirm HLA-C*06 and DRB1*07 as the most important genetic risk factors for psoriasis." (PMID 23184486, 2013). "Subjects expressing HLA-C*06 were significantly younger at the time of onset of psoriasis (24 ± 13.6 years) than the individuals without this allele (32.4 ± 14.1 years), P = 0.01." (PMID 23690822, 2013).
psoriasis (continued). "This explanatory model is consistent with several observational studies that patients with severe psoriasis and HIV-1 infection tend to carry the HLA-C*06 and HLA-B*27 alleles, because such alleles would trigger the vigorous immune response associated with exacerbation of psoriasis." (PMID 22577363, 2012). "The lymphocyte associated regions containing HLA-B and HLA-C, harbors two genes that have been implicated in multiple GWAS as modifiers of immunological responses, associated with IL-18 levels, HIV-1 control, vitiligo, multiple clerosis, and psoriasis." (PMID 21738480, 2011). "A stronger association than HLA-C*0602, in particular in HLA-C*0602 negative individuals, is observed with psoriasis in Spanish population." (PMID 22125590, 2011). "However, a recent study indicated that there are distinct differential expression patterns of HLA-C in psoriasis and eczema, suggesting a functional role of HLA-C in psoriasis-related immune response rather than general inflammation." (PMID 18369457, 2008). "In this study, a family-based association analysis of the PSORS1 locus was performed by analyzing 10 polymorphic microsatellite markers from the PSORS1 region as well as HLA-B, HLA-C and CDSN loci in 163 Chinese families of psoriasis." (PMID 18369457, 2008). "Finally, in a first attempt, we searched for initial evidence of whether UVB phototherapy can reduce HLA-C expression on melanocytes in psoriasis lesions." (PMID 40243413, 2025). "Insufficient generation of self-peptides in B cells, which can cross-activate an autoimmune response against melanocytes, due to differences in proteasomal antigen processing and ERAP1 haplotypes, could be one reason that only a fraction of HLA-C*06:02 carriers eventually develop psoriasis." (PMID 41440022, 2025). "A peptide of unknown origin with the sequence VRHDGGNVL, here referred to as the “FALK” peptide, which is known to bind to HLA-C*06:02 as it was formerly isolated from an HLA-C*06:02+ lymphoblastic B cell line, served as a reference unrelated to psoriasis pathogenesis." (PMID 38524140, 2024). "The other limitation of our study lies in the heterogeneity of the psoriasis clinical phenotypes described in our patients that may explain the lack of association between HLA-C alleles and disease severity; MTX treatment outcome could also be assessed." (PMID 36826011, 2023). "Ankylosing Spondylitis (AS), Psoriasis (Ps), Birdshot Chorioretinopathy (BSCR) and Behçet’s disease (BD) are referred as “MHC-I-opathies” as they share an association with HLA-class I genes, in particular HLA-B*27, HLA-C*06:02, HLA-A*29:02 and HLA-B*51, respectively." (PMID 33348540, 2020). "The authors concluded that along with the presence of psoriatic arthritis, studying HLA-C*06:02 could be of great help in seeking the best first-line treatment for psoriasis patients also supporting the hypothesis that HLA-C*06:02 positive patients may present a different endotype of psoriasis." (PMID 33419370, 2020). "One possible explanation for the close relationship of this biomarker with treatment response could be that HLA-C*06:02 patients suffer from an endotype of psoriasis which is highly dependent on IL12/23 signaling that would make them more sensitive to the blockade of this pathway." (PMID 33419370, 2020). "A study of 712 patients with PsA and 335 patients with psoriasis confirmed not to have arthritis by a rheumatologist demonstrated that the HLA alleles B*08, B*27, and B*38 are risk factors for the development of PsA, whereas HLA-C*06 is “protective”28." (PMID 31583079, 2019). "Additionally, we showed a HLA-C*06:02-independent gender-related effect of the rs887466A allele which was protective against psoriasis in males (OR = 0.61, p = 9.2e−005), but not in females (p = 0.66)." (PMID 29589160, 2018).
psoriasis (continued). "This healthy carrier from the Eskin-Schwartz report is negative for the three additional CARD14 variants and for the 06:02 allele at the HLA-C locus, suggesting that genetic cofactors as well as environmental triggers might be required for CARD14-induced psoriasis." (PMID 30386326, 2018). "However, there is a lack of evidence confirming their direct involvement in the development of psoriasis, and none of the candidates are convincingly associated with psoriasis independent of HLA-C." (PMID 23184486, 2013). "We found that the five most significant amino acid positions for psoriasis occurred at 3 positions within HLA-B (residue 97 [p = 1.58×10−53], residue 67 [p = 4.00×10−45], and residue 70 [p = 1.35×10−40]) and 2 positions with HLA-C (residue 156 [p = 3.89×10−51] and residue 97 [p = 4.56×10−45])." (PMID 22577363, 2012). "Adjusting for the HLA-C, two additional loci, one near C6orf10 and one near HLA-B/MICA, have significant associations with psoriasis, which were also observed in an independent Han Chinese dataset, suggesting that within the MHC there are at least three genes moderating susceptibility to psoriasis." (PMID 19680446, 2009). "In conclusion, we provide evidence that two loci within the HLA region in addition to HLA-C, one near C6orf10 and one near HLA-B, are significantly associated with psoriasis, suggesting that within MHC there are at least three genes moderating susceptibility to psoriasis." (PMID 19680446, 2009). "Our analyses also provided further evidence that HLA-Cw*1203 is associated with psoriasis, although it is not clear whether HLA-Cw*1203 is a risk allele itself, or is in LD with the risk allele of another susceptibility gene near HLA-C." (PMID 19680446, 2009). "UVB repressed Oct1, an IFN-γ-independent transcription factor for HLA-C that modulates HLA-C expression and, similar to STAT1 and IRF1, is a transcriptional regulator of differentially expressed genes in psoriasis lesions." (PMID 40243413, 2025). "Finally, we note that our findings appeared to be independent of HLA-C*06:02 status, which not only makes the strongest genetic contribution to psoriasis susceptibility but critically also predicts response to both adalimumab and the IL-12/23 inhibitor ustekinumab." (PMID 36810251, 2023). "Thus, HLA-C*07 could be a biomarker of late psoriasis onset in the Moroccan population." (PMID 36826011, 2023). "Gene–gene interaction (e.g., between HLA-C and ERAP1) in the psoriasis context has been reported in various populations." (PMID 36425068, 2022). "CCHCR1 is located 110 kb away from the HLA-C locus and is positioned between the CDSN and SC1 genes, and it has also been thought to be involved in the pathogenesis of psoriasis in a transgenic mouse model." (PMID 34356904, 2021). "The influence of HLA-C*06:02 status on the efficacy and safety of secukinumab was studied in a phase III clinical trial of patients with moderate-to-severe psoriasis (SUPREME study)." (PMID 33419370, 2020). "Therefore, HLA-C may be responsible for the expression profiles of genes important to psoriasis." (PMID 29292715, 2017). "In a recent GWAS, the HLA-C gene was associated with type I psoriasis (p = 2.97E − 18 for rs1265181, p = 2.58E − 15 for rs12191877, p = 1.84E − 15 for rs4406273, and p = 1.10E − 07 for rs2395029), but not with type II psoriasis after application of the Bonferroni correction." (PMID 26613086, 2015). "Likewise, genes located farther from HLA-C at the centromeric end, including TNF-α (tumor necrosis factor-alpha), AGER (receptor of advanced glycosylation end product-specific receptor), HLA-DRB1, HLA-DQA1 and HLA-DQB1, have also been found to be associated with psoriasis." (PMID 19680446, 2009). "The HLA-C gene, located within the major histocompatibility complex (MHC) region on chromosome 6, is the major genetic determinant of psoriasis." (PMID 19680446, 2009).
psoriasis (continued). "As far as we know, no research has been conducted on the HLA-C allelic frequencies in Moroccan psoriasis patients." (PMID 36826011, 2023). "While the hypermethylation of promoters leads to HLA class I antigen downregulation in cancer, the aberrant promoter methylation cannot explain the high expression of HLA in endometriosis and HLA-C in psoriasis." (PMID 36974156, 2023). "Although a considerable number of studies have investigated the response to biologics in patients with psoriasis, the identified genes are not commonly replicated in other/validation studies, with the exception of HLA-C." (PMID 37631238, 2023). "Accordingly, the main risk factors for Ankylosing Spondylitis (AS), prototype of the Spondyloarthropathies (SpA), the Behçet’s disease (BD), the Psoriasis (Ps) and the Birdshot Chorioretinopathy (BSCR) are HLA-B*27, HLA-B*51, HLA-C*06:02 and HLA-A*29:02, respectively." (PMID 33348540, 2020). "Psoriasis prevalence in Japan is one of the lowest compared with worldwide populations (0.1–0.3%), and HLA-C*06:02 is almost absent within the Japanese population (<0.5%)." (PMID 29760713, 2018). "Moreover, epistatic interactions between HLA-C*06 and LCE3BC loci were reported within the context of psoriasis." (PMID 27919236, 2016). "Association of ERAP1 with AS is restricted to individuals bearing the HLA-B risk factor for this disease, HLA-B27, whereas in psoriasis the relationship between ERAP1 and HLA-C remains unclear." (PMID 25019531, 2014). "Our results suggest that the primary association with HLA-C*06 and HLA-DRB1*07 is with psoriasis and not with PsA per se." (PMID 23184486, 2013). "In vitro data suggest that streptococcal factors influence T-cell function in psoriasis in a HLA-dependent manner, but studies designed to measure the HLA-C/Streptococci interaction are lacking." (PMID 19480679, 2009). "This may indicate that primarily HLA-C*06:02 SNPs are driving stress as a psoriasis trigger in non-European and non-Asian individuals." (PMID 39261909, 2024). "However, HLA-C*06:02 only accounted for 6.7% of the genetic heritability found in psoriasis, suggesting the importance of other HLA genes and non-HLA genes in disease progression." (PMID 37323656, 2023). "Further studies suggested that the hypermethylation of HLA-C could be involved in the pathogenesis of psoriasis by not affecting the expression of HLA-C." (PMID 36193416, 2022). "Moreover, the intergenic variant rs10484554*A, which is in LD with HLA-C (r2 ≥ 0.8), was significantly associated with AIDS non-progression (P = 6.27 × 10–8) and with susceptibility to psoriasis (OR = 4.66, P = 4 × 10–214)." (PMID 28449694, 2017). "GWAS have identified 40 loci in patients with psoriasis, many of which are related to immune function, including the endoplasmic reticulum aminopeptidase 1 (ERAP1), whose product is relevant to peptides binding to the MHC class I molecules, especially HLA-C*0602 and HLA-B*2746." (PMID 27928500, 2016). "Genes telomeric to HLA-C were overexpressed in psoriasis but not in PsA subphenotypes." (PMID 24600518, 2014). "In addition to classical HLA genes such as HLA-C, HLA-B and HLA-DQA2, we also find association of non-HLA genes in the MHC region such as POU5F1, NFKBIL1, NOTCH4, MICA, IER3 and OR12D2 with psoriasis." (PMID 22125590, 2011). "However, it is not known whether there are other psoriasis loci within the MHC in addition to HLA-C." (PMID 19680446, 2009). "While data on HLA-C*06:02 carriage and response to IL-23p19 inhibitors is not available, the fact that our two BLP cases were negative for HLA-C*06:02 may indicate that the IL-23 pathway is active in psoriasis irrespective of HLA-C*06:02 status." (PMID 40125006, 2025).
autoimmune disease (147 papers, 2006 to 2025). A disorder resulting from loss of function or tissue destruction of an organ or multiple organs, arising from humoral or cellular immune responses of the individual to their own tissue constituents. "For HLA-C alleles showing association with both disease classes, the direction of association was discordant between autoimmune disease (protective) and infections (risk)." (PMID 34059071, 2021). "High expression of HLA-C has been associated with protection against infections, yet at the same time correlates with autoimmune disease." (PMID 30574149, 2018). "HLA-C*07 has been linked to Graves disease, an autoimmune disorder that causes hyperthyroidism; 10 of the RE cases carry HLA-C*07:01:01:01, and six patients carry both HLA-C*03:01:01:01 and HLA-C*07:01:01:01." (PMID 28066418, 2016). "It is also possible that HLA-C’s adaptation to pathogens at the gene expression level may affect HLA alleles related to human autoimmune diseases." (PMID 40300101, 2025). "HLA-C alleles could increase the risk of infection and lower the risk of autoimmune disease by reducing immune reactivity to specific ligands." (PMID 39422492, 2024). "Finally, due to its central role in activating NK cells, HLA-C has been linked mainly to viral infections, autoimmune diseases, and cancer." (PMID 37465164, 2023). "Also, overexpression of the HLA-C gene has previously been associated with low survival expectancy of cancer or the development of autoimmune diseases." (PMID 37465164, 2023). "Most other associations of common genetic risk to PsA and autoimmune diseases lie in the HLA-C*07:01, which is the HLA-C constituent of the the ancestral Caucasian haplotype AH8.1 (the Super B8, HLA-A*01:01-C*07:01-B*08:01-DRB1*03:01-DRB3*01:01-DQA1*05:01-DQB1*02:01)." (PMID 33581710, 2021). "Some alleles, notably two HLA-C alleles, had discordant effects on susceptibility to infection and autoimmune disease, in line with some hypotheses regarding the origins of some autoimmune diseases." (PMID 34059071, 2021). "The human leukocyte antigen (HLA)-C genotype is associated with several human autoimmune diseases." (PMID 32184413, 2020). "Importantly, the HLA-C genotype has been implicated in several autoimmune diseases, including Graves’ disease, psoriasis, and Crohn’s disease." (PMID 32184413, 2020). "High HLA-class I expression enhances the strength of CD8+ T-cell responses, and overexpression of HLA-class I molecules is associated with both better control of viral infections and the onset of autoimmune diseases, an effect particularly prominent for HLA-C." (PMID 40243413, 2025). "HLA-C in the HLA I region is an allele closely associated with SARS-CoV-2 infection and also mediates a variety of autoimmune diseases." (PMID 38400850, 2024). "Vitamin D deficiency is associated with increased autoimmunity and susceptibility to infections; it is important to mention that the relevance of HLA-C in autoimmune diseases has been described in detail in previous studies." (PMID 39257885, 2024). "Furthermore, a high density of eQTLs has been found in the regions proximal to HLA-C and HLA-DR, with effects on the expression of multiple genes of the HLA locus in 3 studied haplotypes, and the HLA alleles associated with different autoimmune diseases all correlate with HLA class II expression." (PMID 33125391, 2020). "Many autoimmune diseases such as type I diabetes, myasthenia gravis, SLE, Sjögren’s syndrome, pemphigus vulgaris, dermato/polymyositis, and vitiligo share HLA associations with PsA, the last being associated with both HLA-C*06:02 and -B*27." (PMID 33581710, 2021). "Some HLA alleles implicated in autoimmune diseases showed association with susceptibility to infections, but the latter associations were generally weaker, or with opposite trends (in the case of HLA-C alleles, but not with alleles of HLA class II genes)." (PMID 34059071, 2021).